NUTM2B (NUT family member 2B)
Synonyms: FAM22B; bA119F19.1
Tractability: No criterion of Open Targets' tractability assessment is met for any kind of drug.
Gene: Protein-coding gene on chromosome 10 (79,703,227 to 79,714,681, forward strand). Ensembl gene ENSG00000188199.
Subcellular location (Human Protein Atlas): Nuclear bodies
Genetic constraint (gnomAD): Loss-of-function variants: 1 observed, 9.54 expected, observed/expected ratio (o/e) 0.1, 90% interval 0.036 to 0.5. That is too few expected variants to judge how well the gene tolerates losing a copy. Missense variants: 43 observed, 374.12 expected, observed/expected ratio (o/e) 0.11, 90% interval 0.089 to 0.15. Synonymous variants: 14 observed, 141.48 expected, observed/expected ratio (o/e) 0.099, 90% interval 0.064 to 0.16.
Homologues: Orthologues: macaque NUTM2A (76% identical), rat Nutm2 (34% identical), mouse Nutm2 (33% identical). Paralogues in human: NUTM2E (99% identical), NUTM2A (98% identical), NUTM2D (89% identical), NUTM2F (72% identical), NUTM2G (71% identical), NUTM1 (41% identical).
Diseases named in the same sentence as NUTM2B in open-access papers:
NUTM2B is named in the same sentence as 14 diseases in open-access papers, as found by Europe PMC text mining. Sharing a sentence is not in itself a finding about the gene and the disease. The quoted sentences say what the papers report.
sarcoma (4 papers, 2023 to 2025). A usually aggressive malignant neoplasm of the soft tissue or bone. "The “BCOR rearranged sarcoma” group consisted of BCOR::CCNB3 (n = 18), BCOR‐ITD (n = 7), YWHAE::NUTM2B (n = 3), and MAML::BCOR STS (n = 1)." (PMID 37212486, 2023). "In this study, they included CIC::DUX4, BCOR-altered, EWSR1::ATF1/CREB1, and YWHAE::NUTM2B sarcomas, as well as fusion-negative SRCSs, reflecting the expanding molecular landscape within this spectrum." (PMID 41514642, 2025). "BCOR immunostain is invariably positive in most BCOR-rearranged sarcomas, including the BCOR::CCNB3, BCOR::MAML3, BCOR-ITD sarcomas, and also in certain non-BCOR-rearranged sarcomas, such as YWHAE::NUTM2B sarcomas." (PMID 40705064, 2025).
endometrial stromal sarcoma (2 papers, 2020 to 2021). "This gene and its highly similar homolog NUTM2B have previously been identified in endometrial stromal sarcomas forming in-frame fusion with YWHAE and small round cell sarcomas forming in-frame fusion with CIC." (PMID 34440129, 2021).
submandibular gland tumor (1 paper, 2025). "The one recently reported case (4.2 cm NFATC2::NUTM2B fused submandibular gland tumor in a 68‐year‐old male, reported as carcinoma with myoepithelial features and treated by surgery + adjuvant radiotherapy) had an uneventful course at 20 months follow‐up." (PMID 40944358, 2025).
tumor (6 papers, 2015 to 2025). "For genes such as NUTM2B, the absolute expression differences between SV-associated and other patients may be relatively small, but still statistically significant, even when correcting for expression differences by tumor tissue of origin." (PMID 38442712, 2024). "We describe four myoepithelial‐like neoplasms of salivary (two) and pulmonary (two) origin, carrying recurrent NFATC2 fusions involving NUTM2B (three) and NUTM2A (one) as fusion partners." (PMID 40944358, 2025). "NUTM2A − AS1, NUTM2B − AS1, SNHG3, and THUMPD3 − AS1 were found to be highly expressed in tumor samples." (PMID 35615532, 2022). "Finally, NUTM2A − AS1, NUTM2B − AS1, SNHG3, and THUMPD3 − AS1 were identified to be highly expressed in tumor samples and were negatively correlated with prognosis." (PMID 35615532, 2022). "However, insufficient frequency of YWHAE, NUTM2A, and NUTM2B gene rearrangement and absence of mutation in both the c-kit and PDGFRA genes suggested that this tumor should be categorized as epithelioid leiomyosarcoma." (PMID 28288693, 2017).
NUTM2B also shares sentences with these, for which no sentence is quoted: cancer (2 papers); dermatofibrosarcoma protuberans (1); head and neck neoplasm (1); inflammatory myofibroblastic tumor (1); Meckel -Gruber Syndrome (1); myoepitheliomas (1); renal clear cell sarcoma (1); salivary gland neoplasm (1); soft tissue sarcoma (1); solitary fibrous tumor (1).